RPL23A (ribosomal protein L23a)
Description:
Component of the large ribosomal subunit. The ribosome is a large ribonucleoprotein complex responsible for the synthesis of proteins in the cell. Binds a specific region on the 26S rRNA.
Synonyms: L23A; uL23; MDA20
Tractability: Small molecule: an approved drug acts on it; a structure with a bound ligand is known; a high-quality ligand is known. PROTAC: UniProt records ubiquitination sites on it; ubiquitination databases record sites on it; its protein half-life has been measured; a small molecule that binds it is known. Other modalities: a drug acting on it is in phase 2 or 3 trials.
Target class: Other cytosolic protein
Gene: Protein-coding gene on chromosome 17 (28,719,983 to 28,724,359, forward strand). Ensembl gene ENSG00000198242.
Subcellular location: Cytoplasm; Nucleus
Subcellular location (Human Protein Atlas): Cytosol; Endoplasmic reticulum; Nucleoli fibrillar center
Pathways (Reactome):
Metabolism of proteins: Eukaryotic Translation Termination; Formation of a pool of free 40S subunits; GTP hydrolysis and joining of the 60S ribosomal subunit; L13a-mediated translational silencing of Ceruloplasmin expression; PELO:HBS1L and ABCE1 dissociate a ribosome on a non-stop mRNA; Peptide chain elongation; Ribosome Quality Control (RQC) complex extracts and degrades nascent peptide; SRP-dependent cotranslational protein targeting to membrane; ZNF598 and the Ribosome-associated Quality Trigger (RQT) complex dissociate a ribosome stalled on a no-go mRNA
Metabolism of RNA: Major pathway of rRNA processing in the nucleolus and cytosol; Nonsense Mediated Decay (NMD) enhanced by the Exon Junction Complex (EJC); Nonsense Mediated Decay (NMD) independent of the Exon Junction Complex (EJC)
Cellular responses to stimuli: Response of EIF2AK4 (GCN2) to amino acid deficiency
Developmental Biology: Regulation of expression of SLITs and ROBOs
Disease: Viral mRNA Translation
Metabolism: Selenocysteine synthesis
Gene Ontology:
Molecular function: cadherin binding; protein binding; RNA binding; structural constituent of ribosome; TORC2 complex binding; rRNA binding
Biological process: cytoplasmic translation; negative regulation of myoblast fusion; spermatogenesis; striated muscle contraction; translation
Cellular component: cytoplasm; cytosolic large ribosomal subunit; cytosolic ribosome; extracellular exosome; nucleolus; nucleus; cytosol; ribosome; synapse
Genetic constraint (gnomAD): Loss-of-function variants: 2 observed, 17.55 expected, observed/expected ratio (o/e) 0.11, 90% interval 0.046 to 0.36. The upper end of that interval is the gene's LOEUF score, 0.36, which puts it in group 1 of 6, group 1 being the genes least tolerant of losing a copy. Missense variants: 132 observed, 188.97 expected, observed/expected ratio (o/e) 0.7, 90% interval 0.61 to 0.81. Synonymous variants: 63 observed, 69.47 expected, observed/expected ratio (o/e) 0.91, 90% interval 0.74 to 1.12.
Homologues: Orthologues: macaque RPL23A (100% identical), mouse Rpl23a (100% identical), pig RPL23A (100% identical), rat Rpl23al9 (96% identical), tropical clawed frog rpl23a (96% identical), zebrafish rpl23a (94% identical), rat Rpl23a (94% identical), Caenorhabditis elegans rpl-25.2 (62% identical), Caenorhabditis elegans rpl-25.1 (60% identical).
Diseases named in the same sentence as RPL23A in open-access papers:
RPL23A is named in the same sentence as 22 diseases in open-access papers, as found by Europe PMC text mining. Sharing a sentence is not in itself a finding about the gene and the disease. The quoted sentences say what the papers report.
Arthritis (10 papers, 2017 to 2026). Inflammation of a joint. "T cells derived from naive SKG mice were co-cultured with P. copri-stimulated dendritic cells, thereby promoting the production of IL-17 in response to the arthritis-associated autoantigen RPL23A, leading to the rapid induction of arthritis." (PMID 38029106, 2023). "Colonization of SGK mice with RA patients’ fecal microbiota leads to increased CD4+ interleukin-17 (IL-17)-producing T cells and enhanced response to arthritis-related autoantigen RPL23a." (PMID 39065155, 2024). "Prevotella contributes to arthritis development in mice by activating autoreactive T cells specific for the arthritis-relevant autoantigen Ribosomal Protein L23a (RPL23A)." (PMID 36779190, 2023). "In mice, Prevotella has also been proposed to contribute to RA development, in this case by both, activating autoreactive T cells specific for the arthritis-relevant autoantigen Ribosomal Protein L23a (RPL23A), and by inducing pro-inflammatory Th17 responses." (PMID 35572569, 2022). "Moreover, these mice harbour elevated interleukin (IL)-17 responses to the arthritis-related autoantigen 60S ribosomal protein L23a (RPL23A) in lymphocytes located in regional lymph nodes and the colon, but not the spleen." (PMID 39339815, 2024). "Instead, the adoptive transfer of CD4 T cells that were reactive to RPL23A could induce arthritis, which suggests the direct arthritogenic effect of CD4 T cells." (PMID 28753982, 2017). "SKG mice with NORA microbiota had an increase in gut Th17 cells and developed more severe arthritis than SKG mice with HC microbiota.SKG mouse spleen naive CD4+ T cells co-cultured with P. copri stimulated DC produce high levels of IL-17 in response to RA autoantigen RPL23A." (PMID 41574450, 2026). "RPL23A has been expressed in fibroblast-like synoviocytes (FLS) in healthy and arthritis synovial tissues and is recognized by autoantibodies from patients with auto-inflammatory RA disease." (PMID 34521416, 2021). "Although the anti-RPL23-A antibody was detected in the sera of SKG mice and in some patients with RA, the autoantibody itself did not have the capacity to induce arthritis in mice." (PMID 28753982, 2017).
hepatoma (3 papers, 2012 to 2021). "The present study was carried out to evaluate the anti-cancer activity of ribosomal protein L23A (RPL23A) from the Giant panda on human laryngeal carcinoma Hep-2 cells and human hepatoma HepG2 cells." (PMID 22408443, 2012). "The mRNA level of RPS8, RPL12, RPL23A, RPL27, and RPL30 was detected as upregulated in hepatocellular carcinoma tissues and cell lines." (PMID 33584809, 2020).
ovarian carcinoma (3 papers, 2015 to 2022). A malignant neoplasm originating from the surface ovarian epithelium. "A seven-hub-molecule-signature model (HIBCH, HIST1H2BK, ALB, EIF3E, RPS20, RRAS2, and RPL23A) from a multivariate regression analysis can predict the survival risks of ovarian cancer." (PMID 35498135, 2022). "A seven-hub-molecule-signature model (RRAS2, HIST1H2BK, ALB, RPL23A, HIBCH, RPS20, and EIF3E) from those 1198 mtDEPs is established to predict the survival time of ovarian cancer." (PMID 35498135, 2022).
melanoma (2 papers, 2011 to 2012). A malignant, usually aggressive tumor composed of atypical, neoplastic melanocytes. "A component of ribosomal proteins, human ribosomal protein L23A (RPL23A), identified as mda20, is one of the genes down-regulated in human melanoma and other cell types treated with IFN-b." (PMID 22408443, 2012). "An earlier study reported that IFN-β down regulated the expression of RPL23A in some melanoma cells to achieve growth suppression." (PMID 21931644, 2011).
anemia (1 paper, 2025). A reduction in the number of red blood cells, the amount of hemoglobin, and/or the volume of packed red blood cells. "RPL23A is a ribosomal component essential for protein biosynthesis, with mutations leading to disorders like anemia and cancer." (PMID 40141456, 2025).
Autoimmunity (1 paper, 2018). The occurrence of an immune reaction against the organism's own cells or tissues. "It has been suggested that RPL23A and HIST2H2BE play a central role in the progression from normal liver cells to PBC&PSC, so we propose that RPL23A and HIST2H2BE are potential drug targets that might overcome the defects in autoimmunity and the subsequent dysfunction in metabolism." (PMID 30344796, 2018).
breast carcinoma (1 paper, 2017). "We identify RPSA, RPS5, RPS20, RPL5, RPL11 and RPL23A as six interesting cancer driver candidates and show a tumor suppressor role for RPL5 in the context of breast cancer." (PMID 28147343, 2017).
co-infection (1 paper, 2022). "After co-infection, several cell proliferation-related assays including EdU assays, CCK-8, and colony formation were performed, and the results indicated that upregulated RPL23A could attenuate the effects on CRC cell proliferation induced by HERC3 overexpression and vice versa." (PMID 35637966, 2022).
influenza (1 paper, 2025). An acute viral infection of the respiratory tract, occurring in isolated cases, in epidemics, or in pandemics; it is caused by serologically different strains of viruses (influenzaviruses) designated A, B, and C, has a 3-day incubation period, and usually lasts for 3 to 10 days. "For influenza, discriminatory ribosomal genes included RPL7A, RPL13, RPL18, RPL23A, RPLP2, RPS2, and RPS4X." (PMID 41020849, 2025).
laryngeal carcinoma (1 paper, 2012). Carcinoma that arises from the laryngeal epithelium. "Our research showed that ribosomal protein L23A can effectively inhibit human laryngeal carcinoma Hep-2 cells growth or proliferation activity." (PMID 22408443, 2012).
lymphoma (1 paper, 2022). A malignant (clonal) proliferation of B- lymphocytes or T- lymphocytes which involves the lymph nodes, bone marrow and/or extranodal sites. "Besides lymphoma, raised free levels of several RPs (RPS15A, RPL23A, RPS26 and RPS29) have been associated with aggressiveness and bad prognosis also in other malignancies." (PMID 36226068, 2022).
senile dementia (1 paper, 2021). "Recent studies have shown that RPL7 and RPL23A are differentially expressed in senile dementia and may be potential biomarkers." (PMID 33859672, 2021).
cancer (12 papers, 2012 to 2025). A tumor composed of atypical neoplastic, often pleomorphic cells that invade other tissues. "All results of the experiment revealed that the recombinant protein RPL23A exhibited anti-cancer function on the Hep-2 cells." (PMID 22408443, 2012). "The present study was carried out to evaluate the anti-cancer activity of Ribosomal Protein L23A (RPL23A) from the Giant Panda." (PMID 22408443, 2012). "The purpose of this paper was to explore the structure and anti-cancer function of ribosomal protein L23A (RPL23A) gene of the Giant Panda (Ailuropoda melanoleuca)." (PMID 22408443, 2012). "The purpose is to reveal the anti-cancer activity of ribosomal protein L23A (RPL23A) from the Giant panda." (PMID 22408443, 2012). "A recent study identified six ribosomal protein genes as potential cancer drivers in five different cancer types: uL18/RPL5, uL5/RPL11, uL23/RPL23A, uS7/RPS5, uS10/RPS20, and uS2/RPSA82." (PMID 29674660, 2018). "We screened mutation and copy number data of respectively 4926 and 7322 samples from 16 cancer types and identified six altered genes (RPL5, RPL11, RPL23A, RPS5, RPS20 and RPSA)." (PMID 28147343, 2017). "Besides, interferon gamma response and interferon alpha were enriched in the results of GSEA concentrating RPL23A indicating that RPL23A might have significant roles in immune-related pathways, besides, therapies target Myc could also enhance the immunotherapy in cancers." (PMID 35637966, 2022). "Literature review found that circ_SAR1A, circ-EGLN3 and circ_001842 could promote the progression of RCC, while circ_AKT3 and circ_RPL23A exhibited the low expression in RCC and played important roles in cancer suppression." (PMID 36578555, 2022). "However, RPL23A gene from the Giant Panda (A. melanoleuca) has not been reported, especially in aspect of anti-cancer function." (PMID 22408443, 2012).
infection (10 papers, 2013 to 2025). The state of being infected such as from the introduction of a foreign agent such as serum, vaccine, antigenic substance or organism. "Here, we show that ASFV-DP was expressed from early times and accumulated throughout the infection with a subcellular localization typical of the endoplasmic reticulum, colocalizing with the cap structure and interacting with the ribosomal protein L23a." (PMID 29021398, 2017). "The transcript for the ribosomal protein L23a of P. infestans and potato transcripts known to be up (osmotin, 1,3-beta-glucan glucanohydrolase, lipoxygenase) or down regulated (2-oxoglutarate-dependent dioxygenase) in response to infection by a compatible P. infestans isolate served as controls." (PMID 24294214, 2013). "We observed that under all the conditions tested (mock infection, 6 hpi, and 18 hpi), cytoplasmic ribosome proteins from the small (RPS6, RPS14, and RPS3) and large (RPL23a, RPL24, and RPL8) subunits were enriched in the ASFV-DP fraction." (PMID 29021398, 2017).
tumor (8 papers, 2012 to 2025). "Increased expression of various ribosomal proteins (rpS8, rpL12, rpL23a, rpL27, and rpL30) have been associated with tumor growth." (PMID 32973493, 2020). "In one study, patient samples harboring RPL23A amplification displayed 1.5-fold higher average RPL23A mRNA expression levels compared with RPL23A diploid tumor samples." (PMID 38255260, 2024). "In the analysis of 50 tumor-adjacent tissues and paired tumor samples, the RPL23A mRNA expression was upregulated in tumor samples." (PMID 35637966, 2022). "Patient samples harboring RPL23A amplification displayed 1.5 fold higher average RPL23A mRNA expression levels compared to RPL23A diploid tumor samples (Wilcoxon test, W = 3316, p = 0.003)." (PMID 28147343, 2017). "The findings will give scientific support and orientation for research and development of anticancer protein drugs of ribosomal protein L23A recombinant protein and for the development of tumor vaccine for tumor prevention." (PMID 22408443, 2012). "Besides, 50 CRC tumor tissues were used to research the correlation between RPL23A and HERC3 through IHC, and the results indicated that there was a negative correlation between HERC3 and RPL23A." (PMID 35637966, 2022). "In cancerous cells, the ubiquitination of specific RPs can promote tumour invasion, tumour metastasis, and resistance to chemotherapy treatment, thereby contributing to tumour progression (see sections on RPL5, RPL11, RPS3, and RPL23a)." (PMID 40940922, 2025). "Thus, HERC3 could serve as a rigorous tumor suppressor through RPL23A/c-Myc/p21 axis." (PMID 35637966, 2022). "The HPA database shows that the proteins of POL2B, RPS6 and RPL23A are highly expressed in HCC tissues, and are expected to be molecular targets for anti-tumor." (PMID 36439183, 2022).
RPL23A also shares sentences with these, for which no sentence is quoted: HCMV infection (5 papers); viral infection (5); colorectal cancer (1); gastric cancer (1); intervertebral disc degeneration (1); pancreatic cancers (1); prostate carcinoma (1).